BAP1 (BRCA1 associated deubiquitinase 1)
Diseases named in the same sentence as BAP1 in open-access papers (continued):
Sharing a sentence is not in itself a finding about the gene and the disease.
mesothelioma (continued). "Third, BAP1-proficient mesothelioma and ccRCC cells are more sensitive to TG2-179-1 than their BAP1-deficient counterpart cells." (PMID 36754982, 2023). "Lifetime cancer risks for individuals with a BAP1 GPV (henceforth referred to as BAP1 carriers) are reported to be 20–25% for mesothelioma, uveal and cutaneous melanoma, with lower lifetime risks reported for renal cell carcinoma and other associated cancers." (PMID 37607989, 2023). "Previously, we and others have shown that EZH2 inhibition is effective in BAP1-deleted mesothelioma." (PMID 36657447, 2023). "Conversely, there is some evidence that individuals with mesothelioma and BAP1 GPV have a better survival." (PMID 37607989, 2023). "BAP1 defective expression is routinely used to aid in distinguishing mesothelioma from reactive mesothelial proliferations, with a relatively low sensitivity (42–65%), but a specificity of 100%." (PMID 35204459, 2022). "Although the tumor genome of sporadic mesothelioma patients has been extensively investigated, the tumor genome of patients affected by BAP1-TPDS has yet to be systematically characterized." (PMID 35885614, 2022). "The prevalence of germline BAP1 alterations in unselected patients with metastatic uveal melanoma ranges from 2 to 8%, whereas the prevalence in patients with mesothelioma was 4.4%." (PMID 35320498, 2022). "Two of the most frequently mutated tumor suppressor genes in mesothelioma are neurofibromatosis type 2 (NF2) and BRCA1-associated protein-1 (BAP1) genes." (PMID 35216091, 2022). "EZH2 inhibitors reduces proliferation of BAP1-mutant mesothelioma cell lines, while platinum-based drugs and PARP-1 inhibitors should be able to target cancer cells with defective DNA repair mechanisms." (PMID 36318367, 2022). "The study of the BAP-1 status in the pleural specimens must be conducted routinely because it allows the diagnosis of mesotheliomas in situ (MIS)." (PMID 36553016, 2022). "BAP1 alterations are correlated with environmental carcinogen exposure and BAP1 knockout mice showed increased incidence of mesothelioma after chronic asbestos exposure." (PMID 36138075, 2022). "Preclinical models of mesothelioma confirm that specific alterations can lead to different outcomes, for example, CDKN2A loss leads to poor outcomes and BAP1 alterations in combination with NF2 and CDKN2A/B to rapid disease onset." (PMID 36138075, 2022). "A recent Phase IIa clinical trial showed some activity of PARP inhibitors in mesothelioma patients with BAP1 and BRCA2 alterations (MiST1 trial)." (PMID 36138075, 2022). "The aim of this study was to characterize the ADAR‐dependent RNA editing landscape in human mesothelioma and put it into context with known BAP1 status." (PMID 36221913, 2022). "In sporadic patients with mesothelioma, the prevalence of BAP1-TPDS is about 1%, which is higher than what we found in our previous study performed on patients highly exposed to asbestos (<0.001%,)." (PMID 35885614, 2022). "Somatic BAP1 deletions are recognised as early events in mesothelioma development, and the combination of germline and somatic mutation in this pathway would have likely impacted downstream cell cycle regulation and DNA repair." (PMID 34948918, 2021). "The importance of BAP1 genetics in the development and prognosis of mesothelioma has been extensively reviewed elsewhere." (PMID 34226685, 2021). "To investigate the pathophysiological conservation and relevance of this model, we made use of a BAP1 null mesothelioma cell line (IST-MES2) in which we stably re-expressed BAP1 WT or the catalytic C91S mutant." (PMID 34186021, 2021). "To date, there are no studies demonstrating the correlation between SETDB1 and the three most frequent mutated genes (BAP1, NF2, and CDKN2A) in mesothelioma." (PMID 34299035, 2021).
mesothelioma (continued). "Individuals with constitutional pathogenic variants in the BAP1-gene have a BAP1-Tumor predisposition syndrome (BAP1-TPDS), which is associated with an increased risk of uveal melanoma, mesothelioma, cutaneous melanoma and clear cell renal carcinoma." (PMID 33919815, 2021). "One of the main concern about DNA damage and mesothelioma has been the assessment of the role of BAP1 in sensing cells to PARPi." (PMID 34249695, 2021). "Here we demonstrate that BAP1 wild-type mesothelioma cells were rendered sensitive to EPZ-6438 upon SIRT1 (Sirtuin 1) silencing/inhibition or when cultured as multicellular spheroids, in which SIRT1 expression was lower compared to cells grown in monolayers." (PMID 34277422, 2021). "In BAP1 tumor predisposition syndrome, clear cell renal cell carcinoma (RCC) is frequently associated with melanoma and/or mesothelioma, while germline MITF p.E318K alterations are being increasingly reported in melanoma/RCC." (PMID 34767027, 2021). "Hereditary predisposition syndromes associated with the co-occurrence of melanoma and/or mesothelioma and renal cell carcinoma (RCC) include BAP1 tumor predisposition syndrome and tumors associated with MITF p.E318K alterations." (PMID 34767027, 2021). "BAP1 functions as a tumor suppressor in mesothelioma, intrahepatic cholangiocarcinoma (ICC) and renal cell carcinoma (RCC)." (PMID 34201614, 2021). "Molecular abnormalities involved in the development of MPM are germline BAP1 (breast cancer 1-BRCA1-associated protein mutation, resulting in the loss of expression of BAP1, described in familial cases of mesothelioma." (PMID 34206956, 2021). "What is the frequency of melanoma and/or mesothelioma co-occurring with renal neoplasia and of germline alterations of BAP1 and MITF within this cohort?" (PMID 34767027, 2021). "BRCA1-associated protein 1 (BAP1) is a tumor suppressor and its loss can result in mesothelioma, uveal and cutaneous melanoma, clear cell renal cell carcinoma and bladder cancer." (PMID 34591877, 2021). "Patients with a familial germline mutation in BAP1 display a hereditary tumor predisposition syndrome (TPDS) leading to early onset malignancy – most frequently melanoma, mesothelioma, and renal cell carcinoma." (PMID 34504799, 2021). "Two patients with clear cell RCC had germline BAP1 alterations in the setting of cutaneous melanoma and mesothelioma." (PMID 34767027, 2021). "Conversely, BAP1 mutant mesothelioma cell lines resulted significantly less sensitive than BAP1 wild type cells to gemcitabine." (PMID 32226777, 2020). "Another PARP inhibitor, niraparib, is being tested in patients with BAP1 and other DNA damage response (DDR) pathway deficient neoplasms including mesothelioma (NCT03207347)." (PMID 32226777, 2020). "In mice combinatorial deletions of Bap1, Nf2, and Cdkn2a result in aggressive mesotheliomas, defined by stem cell-like potential." (PMID 32392897, 2020). "The four main tumor types strongly associated with the BAP1-tumor predisposition syndrome (BAP1-TPDS) are uveal melanoma, mesothelioma, cutaneous melanoma and renal cell carcinoma." (PMID 33396957, 2020). "BAP1 TPDS is associated with an increased risk of uveal and cutaneous melanoma, mesothelioma, renal cell carcinoma, and several other cancer subtypes." (PMID 32218990, 2020). "The function of BAP1 as a tumor suppressor has been identified in manytumors, including renal cell carcinoma, mesothelioma, uveal melanoma, and variousother malignancies." (PMID 32422649, 2020). "In this study, the chemosensitivity of human mesothelioma cell lines carrying BAP1 wild-type (WT), mutant and silenced was analysed." (PMID 30669483, 2019).
mesothelioma (continued). "BAP1 germline mutations have been associated with a syndromic disease characterized, among others, by the presence of CMM, uveal melanoma, mesothelioma, renal cell carcinoma, and other cutaneous neoplasia." (PMID 31382929, 2019). "Based on the data from Shrestha and colleagues, examination of BAP1 status in relation to immunotherapy response in mesothelioma is warranted." (PMID 30914057, 2019). "Prior studies of mesotheliomas, performed using a single omic platform, have established BAP1 inactivation as a key driver event in mesotheliomas." (PMID 30777124, 2019). "A similar approach involving quantitative MS combined with gene arrays was used in NCI-H226 mesothelioma cells to assess EMT pathway in the frame of BAP1 tumour suppressor activity influence." (PMID 31781477, 2019). "Confirmation of the clinical value of BAP1 as a targeting biomarker for death receptor agonists in early phase clinical trials of mesothelioma is the first priority." (PMID 29345617, 2018). "The germline BAP1 mutation is associated with an increased risk of UM, mesothelioma, cutaneous melanoma, meningioma, RCC and MBAITs (melanocytic BAP1-mutated atypical intradermal tumors) and is known as BAP1 hereditary cancer predisposition syndrome." (PMID 30395583, 2018). "A chemical screen in mesothelioma cell lines identifies a BAP1-mutant population sensitised to the death receptor ligand rTRAIL." (PMID 29345617, 2018). "Following reports of germline BAP1 mutations in familial uveal melanoma, cutaneous melanoma and mesothelioma, it was recognised that RCCs are also part of the BAP1 tumour syndrome spectrum." (PMID 29680948, 2018). "BAP1 mutations have been found in other aggressive cancers, including skin-derived melanomas, mesotheliomas, and renal cell carcinomas, suggesting a general role for BAP1 as a suppressor of metastasis in cancer." (PMID 30400891, 2018). "Increased levels of intracellular ROS as well as hypersensitivity to extracellular ROS for wild-type BAP1-expressing cells is particularly relevant to mesothelioma." (PMID 29069806, 2017). "Our results support a major role of BAP1 in regulating cell morphology, cell migration and mitochondrial respiration in mesothelioma." (PMID 29069806, 2017). "Germline mutation of the BRCA1 associated protein-1 (BAP1) gene has been linked to uveal melanoma, mesothelioma, meningioma, renal cell carcinoma and basal cell carcinoma." (PMID 28062663, 2017). "Immunostaining of both LFA-and LNT-induced mesotheliomas for the tumor suppressor protein BAP1 revealed positive cytoplasmic staining in all tumor cells and positive nuclear staining in ∼10% tumor cells (data not shown)." (PMID 29112861, 2017). "Quantitative mass spectrometry and gene expression arrays were used to investigate the consequences of BAP1 expression modulation in the NCI-H226 mesothelioma cell line." (PMID 29069806, 2017). "The Bap1 protein’s neo-antigen has potential for the personalized molecular diagnosis and precise subtyping of malignancies such as mesothelioma." (PMID 27187383, 2016). "Among mutations in known mesothelioma-related genes, such as NF2 and CDKN2A, somatic mutations in BAP1 are the most common recurrent events." (PMID 27187383, 2016). "Endogenous HDAC2 directly correlates with BAP1 across a panel of lung cancer cell lines, and is downregulated in mesothelioma cell lines with genetic BAP1 inactivation." (PMID 25970771, 2015). "In mesothelioma, BAP1 loss is more common in a clinical sub-group that exhibit less evidence of EMT, but on asbestos exposure BAP1+/– mice develop more aggressive tumors, that invade other organs, than their wild-type littermates." (PMID 25970771, 2015). "Deletions of chromosome arms 3p, 9p and 22q, which include the tumor suppressor genes BAP1, CDKN2A, and NF2, respectively, have all been linked to mesothelioma." (PMID 25952750, 2015).
mesothelioma (continued). "As predicted, HDAC2 expression was low in BAP1 null mesothelioma cell lines and overall showed a tight correlation with BAP1 expression status." (PMID 25970771, 2015). "To identify families with the BAP1 cancer syndrome, we screened patients with family histories of multiple mesotheliomas and melanomas and/or multiple cancers." (PMID 26683624, 2015). "These new mouse data, in several different genetic backgrounds, do not support the conclusion that germline Bap1 heterozygous mice have an increased risk of mesothelioma compared to their WT littermates." (PMID 40867321, 2025). "Moreover, BAP1 controls cell cycle checkpoints, enhancing mesothelioma progression when BAP1 is lost." (PMID 40361508, 2025). "Spontaneous mesotheliomas were detected in 2/329 Bap1-mutant and 0/227 wild-type mice." (PMID 40867321, 2025). "Additionally, mesothelioma is characterized by the frequent loss or mutation of tumor suppressor genes such as cyclin dependent kinase inhibitor 2 A (CDKN2A), BRCA1 associated protein 1 (BAP1), neurofibromin 2 (NF2), and cullin 1 (CUL1)." (PMID 40223054, 2025). "Approximately 10% of mesothelioma patients harbor germline mutations in cancer susceptibility genes, predominantly involving CDKN2A, neurofibromatosis type 2 (NF2), and BRCA1‐associated protein 1 (BAP1)." (PMID 40904706, 2025). "These investigations have demonstrated that exposures to very low doses of crocidolite (total 0.1–0.5 mg, compared to 3–5 mg generally used in such experiments) induced mesotheliomas in 36–47% of heterozygous Bap1-mutant mice versus about 10% of similarly exposed WT littermates." (PMID 40867321, 2025). "However, a marked increase in mesothelioma incidence is observed in Bap1-mutant mice upon even minimal asbestos exposures." (PMID 40867321, 2025). "Because of their inflammatory tumor microenvironment and increased immune signaling, mesotheliomas with BAP1 abnormalities may be able to predict long-term responses to immune checkpoint inhibitors (ICPi)." (PMID 40227645, 2025). "BAP-1 depletion has been shown to increase HDAC1 levels in vitro in mesothelioma cells." (PMID 41375064, 2025). "BRCA1-associated protein 1 (BAP1) is a tumor suppressor gene; its inactivation is observed in 25% of cholangiocarcinoma cases and (in the absence of mesothelioma) it is of potential value for differential diagnosis with very low sensitivity." (PMID 40426891, 2025). "They occur sporadically or in association with the BAP1 tumour predisposition syndrome (BAP1–TPDS), which may be complicated by uveal or cutaneous melanoma, mesothelioma, basal cell carcinoma and renal cell carcinoma." (PMID 39268598, 2025). "While retained BAP1 or MTAP expression does not exclude mesothelioma, the combined loss of both strongly supports malignancy." (PMID 41375066, 2025). "In the absence of a Bap1 mutation, wild-type CD-1 mice develop occasional spontaneous mesotheliomas, whereas WT mice from other strains reported here do not." (PMID 40867321, 2025). "Similarly, Mesothelioma, which, like RCC, is frequently characterized by BAP1 loss, has become a testing ground for the therapeutic implications of PARP inhibitors." (PMID 41440218, 2025). "One such technique to consider is the detection of BAP1 loss, since this is present in up to 60% of human mesotheliomas and is absent in non-neoplastic proliferative mesothelial lesions." (PMID 41472150, 2025). "Therefore, it is essential to further investigate BAP1 expression levels in tumor samples from mesothelioma patients." (PMID 39939955, 2025). "Specifically, loss of BAP1 function reduces the deubiquitylation of HDAC1, which interacts with HMGB1 and BAP1 as a trimer, leading to hyperacetylation and nuclear release of HMGB1, thereby promoting mesothelioma progression." (PMID 40559922, 2025). "Notably, these Bap1+/− mice developed mesothelioma at a rate comparable to WT mice that were exposed to 8- to 10-fold higher doses of asbestos." (PMID 40867321, 2025).
mesothelioma (continued). "Three of the most frequent clonal genetic alterations that occur in human mesothelioma cells are somatic mutations and deletions of the tumor suppressor genes BAP1, CDKN2A/B, and NF2, and germline mutation of BAP1 is a well-established genetic risk factor for mesothelioma." (PMID 38784478, 2024). "We determined dose–response curves of ATM inhibition for the tested human mesothelioma cell lines showing that there is no clear difference in sensitivity between Bap1-deficient and proficient cell lines for ATM inhibition only." (PMID 38519707, 2024). "BAP1 is one of the most frequently altered genes in mesothelioma patients." (PMID 38519707, 2024). "BAP1 is a tumor suppressor gene that contains binding domain for BRCA1 and BARD1; germline mutations predispose patients to a variety of cancers including uveal and cutaneous melanoma, mesothelioma, lung adenocarcinoma, meningioma, and renal cell carcinoma." (PMID 38700789, 2024). "In vitro data showed sensitivity to the combined inhibition in BAP1-deficient mesothelioma and uveal melanoma tumor cell lines but not for BAP1-proficient subtypes." (PMID 38054839, 2024). "Loss of BAP1 protein expression predicted longer survival (16.1 months vs. 6.3 months) in patients with mesothelioma in one study, but was not prognostic in another." (PMID 39267830, 2024). "We found that, likewise to mesothelioma, BAP1-mutated uveal melanoma cells are hypersensitive to this drug combination whereas BAP1 wildtype cells are not." (PMID 38054839, 2024). "is the only other publication discussing BAP1 differentiation using image analysis for mesothelioma; however, the work presented here is novel as it is the first to synergistically implement a deep learning model for tumor segmentation and machine learning models for BAP1 classification." (PMID 39669009, 2024). "To investigate whether a combined treatment of EZH2 and FGFR inhibition is effective, we made use of mouse mesothelioma cell lines derived from our genetically defined BNC (Bap1−/−, Nf2−/−, Cdkn2ab−/−) and NC (Nf2−/−, Cdkn2ab−/−) mice." (PMID 38054839, 2024). "However, BAP1 immunostaining demonstrated nuclear loss and p16-FISH demonstrated homogenous deletion in tumor cells, confirming that the tumor was a mesothelioma." (PMID 39006698, 2024). "We are currently using one such agent, sulforaphane, a natural compound found in cruciferous vegetables such as broccoli that is an indirect antioxidant with cytoprotective properties, to test its efficacy in preventing mesothelioma in asbestos-exposed Bap1+/− mice." (PMID 38784478, 2024). "Since BAP1 (BRCA1-Associated Protein 1) and NF2 (Neurofibromin 2) are frequently mutated in mesothelioma and exploit fundamental functions in regulating cell death, proliferation, and chromatin organization, their expression was evaluated by immunofluorescence in MSTO-211H and Met-5a cells." (PMID 39204360, 2024). "To get more insight in the potential link between BAP1 loss and reduction in ATM levels, we performed RNA sequencing on the mesothelioma cell lines with an inducible shBAP1 construct and compared these lines to cells transduced with an inducible shRANDOM construct." (PMID 38519707, 2024). "In order to verify whether the efficacy of our combination can be truly attributed to the absence or presence of BAP1 protein expression we used the isogenic mesothelioma cell line NCI-H226." (PMID 38519707, 2024). "BAP1 appears one such biomarker gene which is mutated in a large fraction of mesothelioma and has been used for exploring pharmacologically targetable vulnerabilities for patients lacking BAP1." (PMID 38054839, 2024).